EPIC1 (epigenetically induced MYC interacting lncRNA 1)
Synonyms: Lnc-EPIC1
Gene: Long non-coding RNA gene on chromosome 22 (47,630,827 to 48,023,004, forward strand). Ensembl gene ENSG00000224271.
Diseases named in the same sentence as EPIC1 in open-access papers:
EPIC1 is named in the same sentence as 16 diseases in open-access papers, as found by Europe PMC text mining. Sharing a sentence is not in itself a finding about the gene and the disease. The quoted sentences say what the papers report.
breast carcinoma (12 papers, 2018 to 2025). "Overexpression of lncRNA EPIC1 is associated with poor prognosis in patients with luminal type B breast cancer, and promotes tumor growth and cell cycle progression by interacting with MYC." (PMID 34116677, 2021). "Promoter hypomethylation can also upregulate long non-coding RNA (lncRNA), such as EPIC1, which promotes breast cancer tumourigenesis." (PMID 40358524, 2025). "For example, higher expression of EPIC1 is correlated with poor prognosis in breast cancer patients." (PMID 32322669, 2020). "In this regard, we have experimentally demonstrated that EPIC1, the top predictive lncRNA for iBET drug response, regulates iBET resistance in breast cancer by regulating MYC transcriptional activity." (PMID 30093685, 2018). "Being selected as a top predictor of iBET resistance by BRCA-specific LENP-iBET model, EPIC1 expression has a significant positive correlation with IC50s of iBET762 in breast cancer cell lines (rho = 0.53, p = 0.002, Spearman’s correlation)." (PMID 30093685, 2018). "We further cloned the full-length human EPIC1 cDNA24 and overexpressed EPIC1 in MCF-7 breast cancer cells and A549 lung cancer cells." (PMID 30093685, 2018). "Notably, breast cancer patients with low EPIC1 showed higher pCR rate (40.7% (n=1)) when treated with TP regimen than patients with high EPIC1 (33.3% (n=1))." (PMID 38576013, 2024). "Together with MYC, lncRNA EPIC1 co‐occupies the promoters of > 97% of EPIC1‐regulated genes involved in cell cycle progression, and thereby regulates transcriptional activity of these genes in breast cancer cells." (PMID 30451365, 2019). "To investigate the EPIC1’s role in regulating the iBET response in cancer cell lines, we knocked down the EPIC1 expression in MCF-7, BT-474 and ZR-75-1 breast cancer cell lines with three EPIC1 siRNAs." (PMID 30093685, 2018).
lung carcinoma (5 papers, 2018 to 2025). "Downregulation of EPIC1 suppresses cell growth, survival, and proliferation and induces apoptosis and cell-cycle arrest in lung cancer cells." (PMID 32322669, 2020). "Overexpression of EPIC1 increased these genes’ expressions, leading to cell growth promotion in lung cancer cells." (PMID 32322669, 2020). "EPIC1 downregulation decrease the expression of Cyclin A1, Cdc20, and Cdc45 in lung cancer cells." (PMID 32322669, 2020). "Similarly, EPIC1 has been reported to be elevated in human lung cancer tissues and gliomas." (PMID 32322669, 2020).
cholangiocarcinoma (2 papers, 2020). A carcinoma that arises from the intrahepatic biliary tree (intrahepatic cholangiocarcinoma) or from the junction, or adjacent to the junction, of the right and left hepatic ducts (hilar cholangiocarcinoma). "In addition, EPIC1 expression level is elevated in cholangiocarcinoma tissues and several cholangiocarcinoma cancer cell lines when compared with adjacent normal samples and normal immortalized cholangiocyte cells, respectively." (PMID 32322669, 2020). "Furthermore, downregulation of EPIC1 leads to inhibition of Cyclin A and Cyclin D and CDK9 in cholangiocarcinoma cells." (PMID 32322669, 2020).
glioma (2 papers, 2020 to 2021). A benign or malignant brain and spinal cord tumor that arises from glial cells (astrocytes, oligodendrocytes, ependymal cells). "Consistently, overexpression of Cdc20 abrogated TMZ sensitivity due to downregulation of EPIC1 in glioma cells." (PMID 32322669, 2020). "Overexpression of Cdc20 reversed the EPIC1 siRNA-mediated inhibition of cell viability in glioma cells." (PMID 32322669, 2020). "In this study, we determined the function of EPIC1 in glioma cells via upregulation or downregulation of EPIC1." (PMID 32322669, 2020). "Here, we found that EPIC1 downregulation inhibited the expression of Cdc20, while overexpression of EPIC1 elevated Cdc20 expression level in glioma." (PMID 32322669, 2020). "Next, to further investigate the role of Cdc20 in EPIC1-mediated tumor progression, we overexpressed Cdc20 in glioma cells after EPIC1 siRNA transfection." (PMID 32322669, 2020). "Our study will provide the evidence for the role of EPIC1 in cell viability, apoptosis, invasion, and drug resistance in glioma." (PMID 32322669, 2020). "In line with this, overexpression of Cdc20 reversed the EPIC1-mediated tumor progression in glioma cells." (PMID 32322669, 2020). "Our data revealed that EPIC1 downregulation by siRNA transfection suppressed cell invasive activity in three glioma cell lines." (PMID 32322669, 2020). "To achieve this goal, we performed cell invasion assay in three glioma cells after EPIC1 siRNA transfection by Transwell inserts with Matrigel." (PMID 32322669, 2020). "Our data showed that downregulation of EPIC1 by siRNA transfection reduced the expression of Cdc20 in three glioma cell lines." (PMID 32322669, 2020). "We measured the cell viability by MTT (3-4,5-dimethyl-2- thiazolyl-2, 5-diphenyl-2-H-tetrazolium bromide) in glioma cells after EPIC1 downregulation or overexpression." (PMID 32322669, 2020). "Our data from MTT assay showed that downregulation of EPIC1 suppressed cell viability in three glioma cell lines." (PMID 32322669, 2020). "After the SNB19, T98G, and U97MG cells were transfected with EPIC1 siRNAs, the histone DNA apoptosis ELISA assay was utilized to measure the cell apoptotic death in glioma cells." (PMID 32322669, 2020). "To determine the role of EPIC1 in glioma cells, we transfected SNB19, T98G, and U97MG cells with EPIC1 small interfering RNA (siRNA)." (PMID 32322669, 2020). "Our results showed that inhibition of EPIC1 suppressed cell viability, induced apoptosis, inhibited cell invasion, and increased cell sensitivity to temozolomide in glioma cells." (PMID 32322669, 2020). "Downregulation of Cdc20 induced cell apoptosis in glioma cells and abrogated EPIC1-mediated inhibition of cell apoptosis in glioma." (PMID 32322669, 2020). "The glioma cells were infected with lentiviruses containing the full length of EPIC1 and transfected with Cdc20 siRNA." (PMID 32322669, 2020). "Histone DNA apoptosis ELISA was conducted to detect the cell apoptosis in glioma cells with EPIC1 upregulation." (PMID 32322669, 2020). "To further investigate the role of EPIC1 in glioma, we used recombinant lentiviruses containing the full length of EPIC1 to upregulation of EPIC1 in SNB19, T98G, and U97MG cells." (PMID 32322669, 2020). "The results from RT-PCR demonstrated that EPIC1 expression level was significantly decreased in three glioma cell lines after EPIC1 siRNA transfection." (PMID 32322669, 2020). "In the present study, we found that overexpression of EPIC1 enhanced the glioma progression, while downregulation of EPIC1 exhibited antitumor activity in glioma, indicating that EPIC1 plays an oncogenic role in glioma." (PMID 32322669, 2020). "Consistently, overexpression of EPIC1 exhibited the opposite effects in glioma cells." (PMID 32322669, 2020). "We further detected the cell apoptosis by ELISA in glioma cells after EPIC1 modulation." (PMID 32322669, 2020). "Lastly, we intended to dissect the mechanism of EPIC1 in glioma progression." (PMID 32322669, 2020).
glioma (continued). "This study identified the molecular mechanism of lncRNA EPIC1-mediated tumor progression in glioma." (PMID 32322669, 2020). "Our results also showed that EPIC1 overexpression increased the resistance of glioma cells to TMZ." (PMID 32322669, 2020). "We found that EPIC1 siRNA transfection increased glioma cells sensitivity to TMZ treatment." (PMID 32322669, 2020). "We found that overexpression of EPIC1 inhibited cell apoptosis in three glioma cell lines." (PMID 32322669, 2020). "We noticed that overexpression of EPIC1 increased cell viability in three glioma cell lines." (PMID 32322669, 2020). "Upregulation of Cdc20 abrogated EPIC1 siRNA-induced apoptosis in three glioma cell lines." (PMID 32322669, 2020). "Consistently, overexpression of EPIC1 increased the Cdc20 expression in three glioma cell lines." (PMID 32322669, 2020). "We further dissected the mechanism of EPIC1-mediated tumor progression in glioma." (PMID 32322669, 2020). "EPIC1 exhibits its functions through targeting Cdc20 in glioma cells." (PMID 32322669, 2020). "We found that downregulation of EPIC1 induced cell apoptosis in three glioma cell lines." (PMID 32322669, 2020). "Moreover, our data suggest that EPIC1 exerts its biological functions via targeting Cdc20 in glioma cells." (PMID 32322669, 2020). "We observed that upregulation of EPIC1 increased cell invasive activity in three glioma cell lines." (PMID 32322669, 2020). "In the present study, we aimed to determine the role of EPIC1 in glioma progression." (PMID 32322669, 2020). "Moreover, Cdc20 inhibition retarded cell invasion and abolished EPIC1-mediated enhancement of cell invasive activity in glioma cells." (PMID 32322669, 2020). "In line with this, overexpression of EPIC1 in glioma cells led to resistance to TMA treatment." (PMID 32322669, 2020). "Overexpression of EPIC1 via targeting Cdc20 could be useful in glioma treatment." (PMID 34178658, 2021). "However, the role of EPIC1 and its underlying molecular mechanisms in glioma have not been investigated." (PMID 32322669, 2020). "Moreover, cell invasion was also investigated in glioma cells after EPIC1 overexpression." (PMID 32322669, 2020). "We explored whether EPIC1 modulation could regulate cell apoptosis in glioma cells." (PMID 32322669, 2020). "Thus, inhibition of EPIC1 or Cdc20 could be a potential strategy for overcoming the resistance to TMZ in glioma patients." (PMID 32322669, 2020). "However, the function and mechanism of EPIC1-involved tumorigenesis in glioma is ambiguous." (PMID 32322669, 2020). "Moreover, depletion of Cdc20 abolished EPIC1-mediated TMZ resistance in glioma cells." (PMID 32322669, 2020). "Therefore, targeting EPIC1 might be a useful approach for glioma treatment." (PMID 32322669, 2020). "Thus, we explored whether EPIC1 could be involved in regulation of cell invasion in glioma cells." (PMID 32322669, 2020). "To explore the mechanism of EPIC1-mediated tumorigenesis in glioma cells, we examined the expression level of Cdc20 in SNB19, T98G, and U97MG cells after EPIC1 modulation using western blotting analysis." (PMID 32322669, 2020). "In addition, we explored whether EPIC1 is involved in TMZ resistance of glioma cells." (PMID 32322669, 2020). "To further validate the function of EPIC1 in glioma cells, we measured the cell apoptosis in SNB19, T98G, and U97MG cells after EPIC1 lentivirus infection." (PMID 32322669, 2020). "To define whether EPIC1 is involved in TMZ resistance in glioma cells, we performed the MTT assay in EPIC1 siRNA or EPIC1 plasmid transfected glioma cells followed by TMZ treatment." (PMID 32322669, 2020). "To explore whether EPIC1 controls cell viability in glioma cells, we utilized MTT assay to measure viability of glioma cells after EPIC1 siRNA transfection." (PMID 32322669, 2020). "However, the function and mechanism of EPIC1 in glioma have not been explored." (PMID 32322669, 2020).
hepatocellular carcinoma (2 papers, 2015 to 2023). A malignant tumor that arises from hepatocytes. "Epigenetically induced myc interacting lncRNA 1 (EPIC1) promotes the development of the hepatocellular carcinoma cell cycle by interacting with myc proto-oncogene, bHLH transcription factor (MYC), and overexpression of EPIC1 correlates with a poor prognosis in hepatocellular carcinoma patients." (PMID 38139458, 2023).
ovarian carcinoma (2 papers, 2018 to 2022). A malignant neoplasm originating from the surface ovarian epithelium. "Overexpression of lncRNA EPIC1 activated the AKT-mTORC1 pathway via Myc and caused rapamycin resistance in ovarian cancer." (PMID 36105363, 2022). "Myc was involved in EPIC1-mediated oncogenesis in ovarian cancer cells." (PMID 36105363, 2022). "LncRNA EPIC1 enhanced rapamycin resistance via activation of AKT-mTORC1 pathway in ovarian cancer." (PMID 36105363, 2022). "EPIC1 knockdown in breast and ovarian cancer cells resulted in significant expression change of 4318 genes, which were significantly overlapped with EPIC1-correlated genes in 505 cancer cell lines (p < 0.0001, two-side Fisher’s exact test) (see Methods section)." (PMID 30093685, 2018).
pancreatic cancer (2 papers, 2021). "For instance, knockdown of lncRNA EPIC1 leads to growth suppression and G0/G1 cell cycle arrest in pancreatic cancer cells." (PMID 33618674, 2021). "Lnc-EPIC1 lost its ability to promote proliferation and growth of YAP1-silenced pancreatic cancer cells." (PMID 34178644, 2021).
cervical cancer (1 paper, 2023). A primary or metastatic malignant neoplasm involving the cervix. "For instance, the lncRNA HOXD cluster antisense RNA 1 (HOXD-AS1) was upregulated and promoted cell proliferation in cervical cancer, while lncRNA EPIC1 promoted proliferation and inhibited apoptosis of gallbladder cancer cells." (PMID 36834942, 2023).
colon cancer (1 paper, 2020). "The results of the present study show that Lnc-EPIC1 is overexpressed in human colon cancer and associated with colon cancer cell progression." (PMID 33170148, 2020). "If Lnc-EPIC1-induced colon cancer cell progression is due to association with MYC, it should be ineffective in MYC-depleted cells." (PMID 33170148, 2020). "In order to test the potential effect of Lnc-EPIC1 on colon cancer cell behaviors, siRNA strategy was applied to knockdown Lnc-EPIC1." (PMID 33170148, 2020). "The results of this study show that Lnc-EPIC1 is important for the progression of colon cancer cells." (PMID 33170148, 2020). "In pri-Can-1 colon cancer cells ectopic overexpression of Lnc-EPIC1 increased cell proliferation (EdU incorporation)." (PMID 33170148, 2020). "In other primary human colon cancer cells, pri-Can-2 and pri-Can-3, si-Lnc-EPIC1-s1/2 similarly increased Caspase-3 activity and TUNEL-positive nuclei ratio." (PMID 33170148, 2020). "More importantly, in MYC-KO colon cancer cells Lnc-EPIC1 siRNA or overexpression was completely ineffective on cell behaviors." (PMID 33170148, 2020). "Testing cell viability, using a CCK-8 assay kit, demonstrated that Lnc-EPIC1 silencing by targeted siRNAs decreased viability of colon cancer cells." (PMID 33170148, 2020). "In the primary colon cancer cells Lnc-EPIC1 siRNA largely inhibited cancer cell growth, proliferation, migration and invasion, while inducing cell death and apoptosis." (PMID 33170148, 2020). "Conversely, forced overexpression of Lnc-EPIC1, using a lentiviral construct, further promoted primary colon cancer cell progression in vitro." (PMID 33170148, 2020). "In the primary human colon cancer cells, Lnc-EPIC1 siRNA largely inhibited cancer cell growth, proliferation, migration and invasion." (PMID 33170148, 2020). "MYC target proteins, including cyclin A, cyclin D and CDK9, were downregulated with Lnc-EPIC1 silencing, but upregulated after Lnc-EPIC1 overexpression in colon cancer cells." (PMID 33170148, 2020). "Lnc-EPIC1 expression is significantly elevated in human colon cancer tissues and primary colon cancer cells." (PMID 33170148, 2020). "In the primary human colon cancer cells that were derived from two other colon cancer patients, pri-Can-2 and pri-Can-3, transfection of si-Lnc-EPIC1-s1 or si-Lnc-EPIC1-s2 resulted in over 90% reduction of Lnc-EPIC1 expression." (PMID 33170148, 2020). "Conversely, ectopic overexpression of Lnc-EPIC1 augmented colon cancer cell growth, proliferation, migration and invasion." (PMID 33170148, 2020). "In this study, RIP and RNA pull down assay results confirmed that Lnc-EPIC1 directly binds MYC protein in the primary human colon cancer cells, essential for MYC’s function." (PMID 33170148, 2020). "In pri-Can-2 and pri-Can-3 colon cancer cells, the Lnc-EPIC1-expression vector resulted in significant increase of Lnc-EPIC1 expression." (PMID 33170148, 2020). "Results demonstrated that Lnc-EPIC1 silencing resulted in over 50-60% reduction of colon cancer cell migration and invasion." (PMID 33170148, 2020). "We show that Lnc-EPIC1 expression is elevated in human colon cancer tissues and primary human colon cancer cells." (PMID 33170148, 2020). "As described, two different Lnc-EPIC1 siRNAs, si-Lnc-EPIC1-s1 and si-Lnc-EPIC1-s2 (see previous studies), were transfected to primary human colon cancers (“pri-Can-1”)." (PMID 33170148, 2020). "The percentage of nuclei with positive EdU staining was significantly decreased in Lnc-EPIC1-silenced colon cancer cells, indicating proliferation inhibition with Lnc-EPIC1 silencing." (PMID 33170148, 2020). "RNA-immunoprecipitation and RNA pull-down results confirmed that Lnc-EPIC1 directly binds MYC protein in colon cancer cells." (PMID 33170148, 2020). "Elevation of Lnc-EPIC1 expression was detected as well in primary human colon cancer cells." (PMID 33170148, 2020).
colon cancer (continued). "We hypothesized that forced overexpression of Lnc-EPIC1 could further promote colon cancer cell progression in vitro." (PMID 33170148, 2020). "Furthermore, Lnc-EPIC1 silencing resulted in 5-6 folds of increase of caspase-3 activity in colon cancer cells." (PMID 33170148, 2020). "Thus, ectopic overexpression of Lnc-EPIC1 further promoted colon cancer cell growth, proliferation, migration and invasion." (PMID 33170148, 2020). "Collectively, overexpressed Lnc-EPIC1 is important for the progression of human colon cancer cells." (PMID 33170148, 2020). "To further support Lnc-EPIC1-mediated colon cancer cell progression is due to MYC association, we show that CRISPR/Cas9-inudced MYC KO mimicked Lnc-EPIC1 silencing-induced activity and inhibited colon cancer cell survival, proliferation and migration." (PMID 33170148, 2020). "Further studies will be needed to explore whether LncRNA EPIC1 expression and its association with MYC are important for the growth of colon cancer cell in vivo, for example using a mouse subcutaneous colon cancer model." (PMID 33170148, 2020). "Further, Lnc-EPIC1 silencing induced significant apoptosis activation in colon cancer cells." (PMID 33170148, 2020). "Therefore, exogenously altering Lnc-EPIC1 expression was ineffective in MYC-KO colon cancer cells." (PMID 33170148, 2020). "In primary human colon cancer cells, pri-Can-1/-2/-3, the MYC (c-MYC) protein immunoprecipitated with Lnc-EPIC1." (PMID 33170148, 2020). "Lnc-EPIC1 siRNA resulted in downregulation of MYC targets, including cyclin A, cyclin D and CDK9 in colon cancer cells." (PMID 33170148, 2020). "Further Lnc-EPIC1 silencing or overexpression failed to alter functions of MYC-knockout colon cancer cells." (PMID 33170148, 2020). "Importantly, Lnc-EPIC1 siRNA (by si-Lnc-EPIC1-s1) or ectopic Lnc-EPIC1 overexpression failed to alter functions of MYC KO colon cancer cells." (PMID 33170148, 2020).
lentivirus infection (1 paper, 2020). Virus diseases caused by the Lentivirus genus. "Our data showed that EPIC1 expression was remarkably increased after EPIC1 lentivirus infection." (PMID 32322669, 2020).
osteosarcoma (1 paper, 2020). A usually aggressive malignant bone-forming mesenchymal neoplasm, predominantly affecting adolescents and young adults. "EPIC1 overexpression causes the suppression of cell viability and invasion in osteosarcoma." (PMID 32322669, 2020). "EPIC1 also inhibits tumor growth in the osteosarcoma xenograft mouse." (PMID 32322669, 2020). "The function of EPIC1 in osteosarcoma is conducted via promotion of MEF2D ubiquitylation." (PMID 32322669, 2020). "Interestingly, one study found that EPIC1 is downregulated in osteosarcoma cell lines and tissues." (PMID 32322669, 2020).